INS (insulin)
Diseases named in the same sentence as INS in open-access papers (continued):
Sharing a sentence is not in itself a finding about the gene and the disease.
sarcopenia (continued). "In sum, MAFLD and sarcopenia embrace shared mechanisms of physiopathology, such as oxidative stress, chronic inflammation, and insulin resistance; in that manner, the presence of one disease contributes to the development of the other." (PMID 40429815, 2025). "Given the central role of muscle in glucose metabolism, creatine supplementation, a well-established tool in sports nutrition, has attracted growing interest for its potential role in improving insulin sensitivity and counteracting sarcopenia." (PMID 40944248, 2025). "Insulin resistance is commonly observed in patients treated with PD and contributes to sarcopenia by impairing the anabolic effects of insulin on muscle, reducing muscle protein synthesis, and facilitating muscle protein breakdown." (PMID 40247955, 2025). "About 75% of glucose disposal is taken by skeletal muscle, a primary organ responsible for insulin-stimulated glucose uptake, which means that sarcopenia patients have a dysfunctional glucose uptake from the circulation." (PMID 38753690, 2024). "Consistent with this, our study also found a significantly higher prevalence of probable sarcopenia among individuals using insulin." (PMID 39310536, 2024). "Amongst T2DM patients, those with incident sarcopenia have worse islet function, insufficient insulin secretion, and more significant blood glucose fluctuations than non-sarcopenic patients." (PMID 38398421, 2024). "Using IPA, KEGG, and GO analysis, we noticed 27 DEPs that overlapped between antioxidant levels, insulin action, metabolic pathways, muscle regeneration, and sarcopenia recovery." (PMID 38541736, 2024). "Our data show improved antioxidant levels, insulin action, metabolic pathways, muscle regeneration, and sarcopenia recovery in the gastrocnemius muscle of the ET mice." (PMID 38541736, 2024). "Future research is supposed to pay attention to “TNF-α,” “insulin resistance,” “mitochondrial autophagy,” “signaling pathways,” and “mechanisms” as pivotal areas in the study of oxidative stress in sarcopenia." (PMID 39588187, 2024). "T2DM can also cause disruptions or even anomalies in mitochondrial activity, hence increasing insulin resistance and speeding the evolution of sarcopenia." (PMID 38643133, 2024). "Gut microbiota can affect muscle mass and muscle function from inflammation and immunity, substance and energy metabolism, endocrine and insulin sensitivity, etc., directly or indirectly establishing a link with sarcopenia." (PMID 38253688, 2024). "Sarcopenia and MASLD/associated fibrosis share common pathogenic mechanisms, including systemic low-grade chronic inflammation, insulin resistance, oxidative stress, hyperammonemia, abnormal myokine secretion, and other pathway disturbances." (PMID 39403588, 2024). "Based on frequency, the two most common keywords are “oxidative stress” and “skeletal muscle,” the themes of this study, pursued by “sarcopenia,” “exercise,” “expression,” “age,” “inflammation,” “body composition,” “older adults,” and “insulin resistance”." (PMID 39588187, 2024). "Fat infiltration in muscle tissues, intramyocellular lipid deposition, and insulin resistance are commonly observed during sarcopenia progression." (PMID 38838088, 2024). "A recent study analyzed the effects of treatment with an olive leaf extract on aging-related sarcopenia and skeletal muscle insulin resistance." (PMID 37049607, 2023). "The pathogenesis of sarcopenia includes systemic inflammation, myostatin signaling, and insulin resistance." (PMID 36983238, 2023). "Sarcopenia results in decreased responsiveness of muscle tissue to insulin, leading to reduced glucose uptake and elevated blood sugar levels." (PMID 38076231, 2023). "Here, we provide evidence that the kidney-muscle crosstalk in sarcopenia is mediated by reduced insulin sensitivity and the activation of the muscle-specific isoform of AMP deaminase, AMPD1." (PMID 36994079, 2023).
sarcopenia (continued). "Nutritional disorders, low levels of branched-chain amino acids (BCAAs), hyperammonemia, abnormal gut microbiota, insulin resistance, and lipid factors are thought to contribute to sarcopenia in patients with chronic liver disease." (PMID 36839249, 2023). "Physical exercise not only directly enhances insulin sensitivity, but also indirectly adjusts body composition, thereby controlling muscle and liver insulin sensitivity and delaying the emergence of sarcopenia." (PMID 38132036, 2023). "The presence of liver cirrhosis contributes to the development of sarcopenia via various factors: portal hypertension complications, elevated hepatic insulin resistance and pro‐inflammatory cytokines." (PMID 36403577, 2023). "As insulin was found to be a deleterious factor in muscle mass and sarcopenia, it was necessary to determine the influence of the type of insulin used, the doses, and the scheme employed." (PMID 38131980, 2023). "The use of antidiabetic drugs showed that the frequency of insulin use was higher in patients with sarcopenia (68.5% vs. 44.3%, p < 0.001) and a lower use of sulfonylureas and biguanides." (PMID 38131980, 2023). "Nonetheless, in longitudinal designs, insulin treatment and reduction of HbA1c levels have been shown to attenuate the progression of sarcopenia in older adults with T2D." (PMID 38131980, 2023). "The analysis of timeline view revealed that protein synthesis and insulin resistance are closely related to muscle mass and strength, which provides a direction to study the mechanism of exercise interventions for sarcopenia." (PMID 36969670, 2023). "Sarcopenia can lead to the inevitable deterioration of skeletal muscle cell structure and biological function and can impair insulin-stimulated glucose disposal into muscle thereby impacting glucose homeostasis." (PMID 37409278, 2023). "The independent risk factors for sarcopenia were serum AST/ALT >1.14, INS*PA <1,833 μU/ml*g/L, FT3 <4.48 pmol/L, VitD <18.5 ng/ml (in male participants), PTC >336 nmol/L, and DBP <81 mmHg (in female participants)." (PMID 35370985, 2022). "In this cross-sectional study of elderly Chinese females aged over 50 years from the WCHAT, FSH, insulin, and the AST/ALT ratio were associated with sarcopenia and risk factors for low muscle mass." (PMID 36419004, 2022). "Then we examined how insulin signaling in skeletal muscle was affected by aging to explore the impact of insulin signaling on the development of sarcopenia." (PMID 36198696, 2022). "Because skeletal muscle is essential for glucose uptake, it is possible that the reduced amount of muscle mass due to sarcopenia, as well as muscle insulin resistance, contributed to the delay in glucose uptake after a CHO‐rich meal." (PMID 35178889, 2022). "On the other hand, increasing age will lead to changes in hormone levels, such as growth hormone, oestrogen, androgens, and insulin, and changes in these hormones are involved in the pathogenesis of sarcopenia." (PMID 36363519, 2022). "In humans, Empa is reported to improve skeletal muscle metabolism, ameliorate insulin sensitivity, and dela T2D-dependent sarcopenia." (PMID 35712355, 2022). "In this cross-sectional study of elderly Chinese females aged over 50 years from the WCHAT, FSH, insulin, and AST/ALT ratio were associated with sarcopenia and risk factors for low muscle mass." (PMID 36419004, 2022). "We investigated the relationships between the levels of fasting insulin and other blood biomarkers related to insulin or lipid metabolism with the presence of sarcopenia in two independent studies." (PMID 36482911, 2022). "INS*PA and AST/ALT have better diagnostic efficacy for sarcopenia, with AUC of 0.705 and 0.680 and with cutoff values of ≤1,500.16 μU/ml*g/L and >1.35, respectively." (PMID 35370985, 2022). "Sarcopenia in turn further decreases the targeting mass of insulin action, reduces insulin sensitivity, and induces glucose dysregulation." (PMID 36482911, 2022).
sarcopenia (continued). "The etiology of uremic sarcopenia is thought to increase proinflammatory cytokines, as well as decrease protein intake, exercise, sex hormones, growth hormones, insulin, vitamin D, and the number of satellite cells." (PMID 35264623, 2022). "More attention should be paid to the levels of AST/ALT and INS*PA in the geriatric population with sarcopenia." (PMID 35370985, 2022). "We therefore studied the relationship of sarcopenia and fasting insulin level in a group of community-living pre-frail frail older persons." (PMID 36482911, 2022). "Our results suggest that insulin is clearly involved in the biological process of sarcopenia in the elderly." (PMID 36482911, 2022). "Multivariate regression of biochemical parameters and muscle mass showed that fasting insulin (OR = 0.854), FSH (OR = 1.016), and AST/ALT ratio (OR = 1.819) were independent risk factors for low muscle mass in female sarcopenia, but the associations were weak." (PMID 36419004, 2022). "Participants with sarcopenia had significantly lower free triiodothyronine, insulin, total protein, albumin, prealbumin, albumin/prealbumin ratio (A/G), alanine aminotransferase, triglycerides, and very low-density lipoprotein concentrations (P < 0.05)." (PMID 36419004, 2022). "The aim of this study was to evaluate the relationship between AST/ALT, INS*PA, and sarcopenia among elderly Chinese participants from the West China Health and Aging Trend (WCHAT) study under the background of China’s aging population." (PMID 35370985, 2022). "Sarcopenia appears to be inextricably intertwined with glucose metabolism, and the maintenance of muscle mass in addition to the balance of insulin sensitivity and insulin secretion plays a critical role in maintaining glucose homeostasis." (PMID 35159148, 2022). "Palmitate induced delayed myoblast differentiation, insulin resistance, cellular senescence, impaired autophagic flux, and increased Atrogin-1 and MuRF1 gene expression, which provide a suitable sarcopenia model." (PMID 34580406, 2021). "On the other hand, myostatin blockade in the muscle of aged animals not only prevents sarcopenia but also increases insulin sensitivity." (PMID 34067004, 2021). "A positive correlation between insulin sensitivity and muscle mass has been found in aged rats and the blockade of sarcopenic markers in old mice is reported not only to prevent sarcopenia but also to increase insulin sensitivity." (PMID 34356299, 2021). "Elderly individuals with the INS/INS genotype had increased chances (p = 0.010; OR: 2.943; 95%CI: 1.301–6.654) for the development of sarcopenia." (PMID 34683186, 2021). "In conclusion, OLE administration to aged rats increases insulin sensitivity in adipose tissue and skeletal muscle and attenuates sarcopenia by decreasing the gene expression of proinflammatory cytokines and muscle atrophy markers." (PMID 34067004, 2021). "The decrease in muscle mass observed in sarcopenia, in turn, leads to a smaller proportion of skeletal muscle participating in insulin-mediated glucose disposal, resulting in insulin resistance." (PMID 33920751, 2021). "Impaired insulin activity in SM is responsible for the altered molecular pathways and clinical manifestations of sarcopenia, which is morphologically expressed by myosteatosis." (PMID 34858322, 2021). "Epidemiological evidence suggests that patients with T2DM and sarcopenia are more frequent insulin users." (PMID 34440727, 2021). "Increased cytokine concentrations in the circulation can activate the ubiquitin-proteasome proteolytic pathway, leading to insulin resistance and muscle wasting, thereby further aggravating sarcopenia." (PMID 35198586, 2021). "On the other hand, age- related reduction of protein metabolism and reduction of insulin mediated suppression of proteolysis leads to development of anabolic resistance and sarcopenia." (PMID 33935962, 2021).
sarcopenia (continued). "Potential mechanisms for this elevated risk of CVD in sarcopenia are increased LDL cholesterol, blood pressure, oxidative stress, proinflammatory cytokines, and decreased insulin sensitivity associated with sarcopenic changes in muscle tissue." (PMID 33001410, 2020). "Muscle strength depends on constant regular glucose and insulin levels in the blood, but in sarcopenia, insulin-resistance occurred." (PMID 31991655, 2020). "Studies have shown that elderly mice treated with myostatin inhibitors for 4 weeks exhibited improvements in sarcopenia and increased skeletal muscle insulin sensitivity." (PMID 32082422, 2020). "The etiologies of sarcopenia is multifactorial and includes inflammation, altered endocrine function, nutritional deficits, physical inactivity and insulin resistance." (PMID 32433712, 2020). "Although thiazolidinedione should theoretically have beneficial effects on skeletal muscle physiology in insulin-resistant subjects, clinical data for the effects of thiazolidinedione on sarcopenia-related parameters are scarce and controversial." (PMID 32695832, 2020). "While the pathophysiology of spinal sarcopenia is complex, several studies have discussed the mechanism which leads to skeletal muscle atrophy, including insulin resistance, myostatin activation, mitochondrial function, and glucocorticoid response." (PMID 32344580, 2020). "In particular, primary skeletal muscle cells from donors with different biological conditions (e.g., aging and insulin resistance) are the best in vitro models for studying sarcopenia or other forms of sarcopenia." (PMID 32498474, 2020). "While these are obviously critical concerns, it should also be noted that sarcopenia is thought to have harmful effects on glucose uptake, since it reduces the amount of available muscle mass for insulin-stimulated glucose disposal." (PMID 31684154, 2019). "Because skeletal muscle is an insulin-response target tissue, sarcopenia patients develop progressive metabolic syndrome." (PMID 31799199, 2019). "The purpose of the current review is to discuss the role of protein to attenuate declines in muscle mass and insulin sensitivity to prevent T2D and sarcopenia in aging adults." (PMID 31555655, 2019). "Some of these changes include sarcopenia, impaired insulin signaling, and imbalances in glucose utilization." (PMID 31684154, 2019). "Reduction of skeletal muscle mass due to sarcopenia lowers glucose metabolism by insulin, leading to insulin resistance, thus making sarcopenia a factor contributing to the onset or exacerbation of diabetes." (PMID 29776338, 2018). "The sarcopenia group also tended to have a lower rate of oral drug use and higher rates of insulin use." (PMID 27832470, 2017). "The anabolic actions of insulin are of interest to people, such as athletes and body builders who want to increase their muscle mass, and to those concerned with preventing sarcopenia." (PMID 28323845, 2017). "One main contributing factor to sarcopenia is the reduced ability to increase skeletal muscle protein synthesis in response to habitual feeding, possibly due to a reduction in postprandial insulin release and an increase in insulin resistance." (PMID 23201839, 2012). "This paradox can be easily understood and resolved based on our H19-IGF2 findings, as young adults display the early phase of growth due to FTO-m6A-H19-IGF2-insulin signaling, whereas the elderly manifest with sarcopenia in the later phase due to excessive insulin signaling and insulin resistance." (PMID 40055326, 2025). "A cross-sectional study identified a low prevalence of definite sarcopenia (1.6%) in elderly subjects with T2D on insulin, according to EWGSOP2 criteria, which may confirm an anabolic effect." (PMID 40870444, 2025).
sarcopenia (continued). "The abundance of Faecalibacterium prausnitzii—known for its important role in the health of the gut microbiota (i.e., in insulin sensitivity, anabolic balance, and inflammation), appears in some studies with a representation up to 5 times lower in individuals with sarcopenia." (PMID 40109720, 2025). "Treatments that preserve or increase lean body mass, such as insulin, may be most effective in people with a low or normal BMI and possible sarcopenia." (PMID 40870444, 2025). "Modulation of PGC‐1α levels in skeletal muscle may help protect against sarcopenia by preserving muscle integrity, enhancing muscle function, improving insulin sensitivity and reducing inflammation and oxidative stress." (PMID 40641114, 2025). "The interaction between NO and insulin during exercise may synergistically affect muscle metabolism, helping maintain muscle mass and attenuating the effects of sarcopenia." (PMID 40364101, 2025). "However, the role of adiponectin in different types of sarcopenia and its connection to insulin sensitivity remains controversial." (PMID 40075777, 2025). "MAFLD and sarcopenia are interconnected by a complex network of pathophysiological mechanisms, such as insulin resistance, skeletal muscle tissue production capacity, chronic inflammatory state, oxidative stress, and mitochondrial dysfunction, which are the main contributors to this relationship." (PMID 40429815, 2025). "Mitochondrial malfunction, frequently encountered in the skeletal muscle of individuals with sarcopenia, impairs energy metabolism and reduces insulin sensitivity, thereby creating a vicious cycle with increased TyG levels that further disrupt metabolic homeostasis." (PMID 41158628, 2025). "Low insulin levels may reduce the anabolic effect of insulin on skeletal muscles, leading to sarcopenia." (PMID 40559405, 2025). "Third, metabolic changes such as sarcopenia, commonly observed in older adults, may influence both insulin sensitivity and β-cell function." (PMID 41003141, 2025). "Furthermore, multiple studies have affirmed that endurance exercise training leads to enhancements in maximal oxygen consumption, mitochondrial function, and insulin sensitivity, thereby mitigating sarcopenia progression." (PMID 39764565, 2025). "Longitudinal studies indicate that insulin-resistant individuals lose muscle mass faster than non-insulin-resistant individuals, which increases their risk of sarcopenia." (PMID 41011274, 2025). "Furthermore, T2DM not only increases the prevalence of MASLD but also contributes to sarcopenia through impaired insulin signaling, reduced anabolic hormone activity, and chronic inflammation that accelerate muscle loss." (PMID 41464593, 2025). "Sarcopenia, in turn, exacerbates IR by reducing tissue responsiveness to insulin." (PMID 39940355, 2025). "Aerobic exercise induced upregulated metabolic pathways through exercise-regulated DEPs in gastrocnemius muscle in a mouse model of type 2 DM-related sarcopenia, directly indicated by increased lipid and glucose metabolism, muscle regeneration, and insulin sensitivity." (PMID 40806701, 2025). "Elevated FGF21 reflects nutritional stress or anabolic inefficiency, such as that observed in sarcopenia, frailty, and insulin resistance, whereas its reduction may indicate improved metabolic homeostasis following nutritional intervention." (PMID 41228530, 2025). "These toxins may also contribute to the onset and development of sarcopenia by interfering with insulin signaling, promoting inflammation and oxidative stress, and other mechanisms." (PMID 41048435, 2025). "In support of this, a reduced level of secreted insulin has been reported as a risk factor for developing sarcopenia in Japanese and Chinese older individuals, regardless of their diabetic status." (PMID 39137152, 2025).